PTCH1 (patched 1)
Diseases named in the same sentence as PTCH1 in open-access papers (continued):
Sharing a sentence is not in itself a finding about the gene and the disease.
ovarian carcinoma (12 papers, 2009 to 2025). A malignant neoplasm originating from the surface ovarian epithelium. "Accordingly, paclitaxel was shown to increase PTCH1 expression, and inhibition of proteasome suppressed PTCH1 levels and increased sensitivity of ovarian cancer cells to the paclitaxel." (PMID 37700842, 2023). "We found that Shh, Ptch1, Smo, and Gli‐1 were overexpressed at the protein level in all ovarian cancer cells compared with HOSEPICs." (PMID 30338663, 2018). "Our study revealed elevated protein expression of Shh, Ptch1, Smo, and Gli‐1 in four ovarian cancer cells compared to HOSEPICs, indicating that Hh signaling is activated in ovarian cancer." (PMID 30338663, 2018). "In addition to these genes, a high risk for ovarian cancer is associated with mutations in the DICER1, VHL, PTCH1, SUFU, SMARCB1, and SMARCA4 genes." (PMID 37685988, 2023). "SHH, HHAT, PTCH1, and PTCH2 overexpression further improved the survival rates of ovarian cancer patients, particularly when optimal debulking was possible." (PMID 40565349, 2025). "We analyzed the mRNA expression profiles of HH-related genes—SHH, HHAT, PTCH1, GLI1, GLI2, GLI3, and SUFU—in two ovarian cancer cell lines." (PMID 40565349, 2025). "The effect of bortezomib on hedgehog transcriptional activity (as determined by PTCH1, GLI1, GLI2 gene expression) in SKOV3TRip2 cells led us to evaluate this compound in other ovarian cancer cell lines." (PMID 25216523, 2014). "To assess their potential prognostic value, we analyzed the correlation between the expression levels of the following eight components of the Hedgehog signaling pathway on the progression-free (PFS) and overall survival (OS) in ovarian cancer: SHH, GLI1, GLI2, GLI3, PTCH1, PTCH2, HHAT, and SUFU." (PMID 40565349, 2025). "Notably, however, PTCH1 and GLI1 exhibited elevated expression levels in the primary ovarian cancer cell lines TOV112D and COV434." (PMID 40565349, 2025). "Using the database Kaplan–Meier plotter, which includes the gene expression and survival data of 1565 ovarian cancer patients, higher expression levels of the genes SHH, PTCH1, PTCH2, and GLI1 displayed better survival correlations, while GLI, GLI3, and SUFU correlated with adverse outcomes." (PMID 40565349, 2025). "To elucidate whether DHA exerted anti‐ovarian cancer effects via inhibiting the hedgehog pathway, we explored the effects of DHA on expression of Shh, Ptch1, Smo, and GLI1 following treatment with DHA for 48 hours." (PMID 30338663, 2018). "Comparative analysis of the difference in ovarian cancer mutation genes between the BRCA1/2 mutation group and the non-mutation group uncovered that FAM175A, EMSY, PTCH1, and HNF1B were significantly highly mutated in the group without BRCA1/2 mutations, particularly PTCH1: c.3907C>T (p.R1303C)." (PMID 38817903, 2024). "Most tumors with elevated expression of Gli1 and PTCH1 had no expression of SMO, suggesting that SMO expression was not responsible for hedgehog signaling activation in ovarian cancer." (PMID 19943941, 2009).
brain cancer (8 papers, 2016 to 2026). A primary or metastatic malignant neoplasm affecting the brain. "Loss of function mutations of the Hedgehog receptor PTCH1 are oncogenic drivers in some skin and brain cancers." (PMID 41748949, 2026). "We asked whether some differentially expressed miRNAs identified through NGS after irradiation of WT and Ptch1+/− GCPs matched with miRNAs whose role in brain cancer development is already well established." (PMID 27626168, 2016).
brain tumor (7 papers, 2015 to 2023). "In fact, we developed a model system involving subcutaneous transplantation into the mouse flank of a brain tumor developed in the Ptch1 heterozygous mouse model." (PMID 37175984, 2023). "The increase of expression of CD15, a marker of brain tumor stem cells, detected by qRT-PCR in the Ptch1+/−/Btg1KO MBs compared with Ptch1+/−/Btg1WT MBs, was confirmed at protein level by immunohistochemical analysis of tumor sections from MBs of the two different genotypes under study." (PMID 32231994, 2020). "Here, we have investigated for the first time the preclinical activity in a brain tumor of a novel, orally bioavailable PI3Kα inhibitor, MEN1611, finding a strong anti-cancer effectiveness against Ptch1+/−/Tis21KO MBs." (PMID 34395258, 2021).
esophageal cancer (6 papers, 2013 to 2025). A primary or metastatic malignant neoplasm involving the esophagus. "Several lines of evidence supported that m6A methylation of PTCH1 facilitated the hepatic stellate cell activation and stem cell properties of esophageal cancer." (PMID 40170839, 2025). "The expression of PTCH1 in a number of malignant tumors, such as breast, liver and esophageal cancer, has been shown to be reduced compared with that in normal tissues." (PMID 24255663, 2013).
esophageal squamous cell carcinoma (6 papers, 2018 to 2025). Esophageal squamous cell carcinoma (ESCC) is a type of esophageal carcinoma (EC) that can affect any part of the esophagus, but is usually located in the upper or middle third. "Further, low Patched-1 expression has been linked to a favorable outcome in some cancer types, i.e. colorectal and esophageal squamous cell carcinomas." (PMID 30521558, 2018). "Interestingly, decreased response to chemotherapy, large tumor size and locoregional progression of esophageal squamous cell carcinoma seem associated to a high expression of Ptch1." (PMID 35631574, 2022). "The overexpression of ATAD2 induces the production of the HH pathway proteins (SHH, SMO, GLI, and PTCH1) in Rb and esophageal squamous cell carcinoma cells (ESCC), which in turn promotes invasion, migration, and proliferation." (PMID 41154392, 2025). "A study published in 2010 reported that high levels of Ptch1 were detected in 76% of biopsy specimens from esophageal squamous cell carcinoma patients that were treated with chemotherapy." (PMID 30110910, 2018). "For example, in esophageal squamous cell carcinoma, BBOX1-AS1 targets miR-506-5p/EIF5A to maintain PTCH1 mRNA stability, leading to increased PTCH1 expression and enhanced cancer development." (PMID 37925403, 2023).
hepatocellular carcinoma (6 papers, 2014 to 2025). A malignant tumor that arises from hepatocytes. "Another study showed that silencing CK2α inhibited the expressions of Gli1 and Patched homolog 1 (PTCH1) in hepatocellular carcinoma, resulting in the inactivation of Hh signaling pathway." (PMID 25422081, 2014). "Others found a mutation in the C-terminal lysine (K575M) that allows for SMO to act independently of PTCH1 as it is unable to bind to and inhibit SMO, leading to uncontrolled signalling and expression of stem cell renewal genes in hepatocellular carcinoma cells (HCC)." (PMID 38920995, 2024).
odontogenic cyst (6 papers, 2018 to 2025). A cyst in the jaw that arises from tissues of tooth development. "Indeed, aberrations in the MAPK, Sonic Hedgehog (SHH), and WNT/β-catenin pathways are well documented in odontogenic cysts and tumors, with BRAF, PTCH1, and CTNNB1 representing the most frequently altered genes." (PMID 41364259, 2025). "The absence of pathogenic PTCH1 mutations in multiple OOC, which was in sharp contrast to the results for OKC, suggested a different entity of odontogenic cysts." (PMID 36242048, 2022).
adrenocortical carcinoma (5 papers, 2018 to 2022). "We showed that Ptch1 contributes to the efflux of doxorubicin and plays an important role in the resistance to chemotherapy in adrenocortical carcinoma (ACC), a rare cancer which presents strong resistance to the standard of care chemotherapy treatment." (PMID 35631574, 2022). "A proof of the specificity of methiothepin to inhibit Ptch1 drug efflux activity only in cancer cells was brought by the quantification of doxorubicin in the tumors and the hearts of mice xenografted with adrenocortical carcinoma cells." (PMID 33810240, 2021). "Further, immunohistochemical (IHC) analysis on adrenocortical carcinoma (ACC) samples from 70 patients showed that Ptch1 was expressed in ACC tumor tissues from all 70 patients." (PMID 30110910, 2018). "We previously showed that Ptch1 drug efflux inhibition enhanced the cytotoxicity of dxr against adrenocortical carcinoma cells, but also that of cisplatin, another well known chemotherapeutic drug, suggesting that both cisplatin and dxr are substrates of Ptch1." (PMID 32526884, 2020). "In this study, we isolated and characterized a small subpopulation of the adrenocortical carcinoma (ACC) cell line H295R that overexpresses Ptch1 and presents more Ptch1 at their plasma membrane, called H295R-PM-Ptc+." (PMID 35631574, 2022).
osteoporosis (5 papers, 2019 to 2025). A condition of reduced bone mass, with decreased cortical thickness and a decrease in the number and size of the trabeculae of cancellous bone (but normal chemical composition), resulting in increased fracture incidence. "Blocking the Hh pathway through the specific deletion of Ptch1 in HOC+ mature osteoblasts leads to severe osteoporosis, and the deletion of SMO in Osx+ or Gli1+ osteogenic progenitors also results in decreased bone formation." (PMID 40141354, 2025). "Osteoporosis (OP) is a common polygenic disorder in the aging population, and several single nucleotide polymorphisms (SNPs) in the alpha-L-iduronidase (IDUA) gene and patched homolog 1 (PTCH1) gene regulate bone metabolism and affect bone mass." (PMID 31275456, 2019). "PTCH1 may be a possible target in the therapy against osteoporosis in specific patients." (PMID 37675799, 2023).
sarcoma (5 papers, 2012 to 2023). A usually aggressive malignant neoplasm of the soft tissue or bone. "In turn, the development of aggressive embryonic sarcomas in both β-catenin GOF and Ptch1 LOF mutants points to a common genetic pathway – providing direction for future studies." (PMID 22792366, 2012).
Stroke (5 papers, 2014 to 2025). Sudden impairment of blood flow to a part of the brain due to occlusion or rupture of an artery to the brain. "The treatment with BHD increased the levels of Shh, SMO, Ptch1 and Gli1 in the right hippocampus and cortex after stroke." (PMID 40973940, 2025). "For two loci that were associated with stroke risk among the South Asians (SAS, COBL) and Africans (AFR, PITCH1), the PTCH1 locus also showed unexpectedly lower frequency in STROMICS compared to the reference populations." (PMID 37479695, 2023). "Therefore, we hypothesize that excessive apoptosis of neuronal cells after stroke leads to a large loss of Ptch1, which activates the Shh signaling pathway in neurons in the ischemic penumbra and then targets the synaptic remodeling-related genes such as Sparc to promote synaptic remodeling." (PMID 37745057, 2023). "Reactive astrocytes of the glial scar expressed Shh, Ptch1 and SMO at 14 d after stroke." (PMID 25341035, 2014).
acute lymphoblastic leukemia (4 papers, 2019 to 2024). Leukemia with an acute onset, characterized by the presence of lymphoblasts in the bone marrow and the peripheral blood. "Hedgehog pathway mutations, particularly those affecting PTCH1 expressions, are quite common (16%) in patients with T-cell acute lymphoblastic leukemia (T-ALL)." (PMID 38611039, 2024).
ameloblastoma (4 papers, 2013 to 2025). The most common odontogenic tumor, arising from the epithelial component of the embryonic tooth and usually affecting the molar-ramus region of the mandible or maxilla. "Twenty-eight FFPE blocks of ameloblastoma cases from Nigerian patients were prepared for antibody processing to PTCH-1 (Polyclonal Anti-PTCH antibody ab39266) and MDM2 (Monoclonal Anti-MDM2 antibody (2A10) ab16895)." (PMID 27386018, 2015). "The objective was to characterize the PTCH-1 genetic profile of Ameloblastoma in Nigerian patients as a first step in investigating its potential for chemotherapeutic intervention." (PMID 27386018, 2015). "The Protein Patched homolog 1 (PTCH-1) is overexpressed in ameloblastoma." (PMID 27386018, 2015).
Anxiety (4 papers, 2018 to 2025). Intense feelings of nervousness, tension, or panic often arise in response to interpersonal stresses. "Firstly, our results showed an increase in exploration behaviors and locomotive functions, together with a decrease of anxiety-linked behaviors in unirradiated Ptch1+/− mice compared to WT controls when both Open Field or Elevated Plus-Maze tests were used." (PMID 34830484, 2021). "It is interesting to note that 8 months after irradiation, the behavior of Ptch1+/− mice showed an inversion, displaying an increased level of anxiety and decreased activity with respect to their unirradiated controls." (PMID 34830484, 2021). "Although anxiety-related behaviors are hippocampal-related function, contribution of Ptch1-dependent alterations in others brain areas to this phenotype cannot be excluded." (PMID 29875630, 2018). "Ptch1+/− mice also show a lower degree of anxiety-like behavior as illustrated by the results of the EPM test, showing increased number of head dips (p = 0.0052) and the time spent in the open arms compared to WT mice (p = 0.031)." (PMID 29875630, 2018). "The patched 1 (PTCH1) gene was associated with variance in depression (P = 1.80 × 10−6) and the chromosome 15 open reading frame 38 (C15orf38) gene was associated with variance in anxiety symptoms (P = 2.00 × 10−7)." (PMID 40494901, 2025). "In this test the irradiated Ptch1+/− mice showed a significant decrease in activity (total distance travelled and number of head dips) and increased anxiety characterized by open arm avoidance (time and number of entries into the open arms) compared to Ptch1+/− unirradiated mice." (PMID 34830484, 2021). "However, it is interesting to note that 8 months after irradiation, the behavior of Ptch1+/− mice showed an inversion, displaying an increased level of anxiety and decreased activity with respect to their unirradiated controls." (PMID 34830484, 2021). "Therefore, subtle and complex interactions between the constitutive Shh pathway activation and radiation injuries, also extending to other brain regions besides the hippocampus, may account for the alteration in anxiety and locomotion activities in irradiated Ptch1+/− mice." (PMID 34830484, 2021). "Given the Shh-dependent alterations in DG neurogenesis, we investigated the behavior of Ptch1+/− mice at 4 months of age, through several tests such as OF (activity and habituation), EPM (anxiety-like levels), MWM (spatial learning and memory) and RAM test (spatial-working memory)." (PMID 29875630, 2018). "Importantly, TLX is a known regulator of cognitive and anxiety-related behaviors and hyperactivity has been documented in TLX knockout mice, pointing to a possible molecular mechanism involving TLX upregulation in behavioral deficit in Ptch1+/− mice." (PMID 29875630, 2018).
asthma (4 papers, 2018 to 2022). "It has also been shown that sonic hedgehog (SHH), an important ligand for PTCH1, is upregulated in the airway epithelium of patients with asthma and is suggested to be involved in airway remodeling." (PMID 36230980, 2022). "Another GWASresearch study demonstrated that linkage between Ptch1 and the Hhip region decreases the performance of the lungs, worsening the asthma-related remodeling; however, the study is uncertain how the Hh pathway can contribute to the pathophysiology of asthma." (PMID 35681469, 2022). "Collectively, our primary cell data showed an upregulation of SHH, SMO, GLI2 and PTCH1 gene expression with epithelial differentiation independent of a diagnosis of asthma." (PMID 36230980, 2022). "In a study by Li and colleagues, a subset of normal lung function genes associated with the hedgehog signaling pathway including the patched homolog 1 (PTCH1) and hedgehog interacting protein (HHIP) predicted lung function decline in white and African American subjects with asthma." (PMID 36230980, 2022). "Allergic response in an ovalbumin (OVA)-induced asthma model was not altered by CD4-specific gene deletion of Ptch1, which points out the activation of the non-canonical Hh pathway in CD4 T-cells." (PMID 35681469, 2022).
bladder cancer (4 papers, 2019 to 2024). "The PTCH1 protein is highly expressed in bladder cancers compared to adjacent normal bladder tissues and has potential value as a prognostic biomarker of bladder cancer." (PMID 36835134, 2023).
breast tumor (4 papers, 2018 to 2020). "Significant over expression of SHH (R.E = 4.4 ± 3.32), DHH (R.E = 4.7 ± 3.46), PTCH1 (R.E = 3.4 ± 3.08) and GLI1 (R.E = 3.8 ± 2.49) were detected in the breast tumour biopsies as compared with controls." (PMID 29329585, 2018).
cervical carcinoma (4 papers, 2021 to 2024). A carcinoma arising from either the exocervical squamous epithelium or the endocervical glandular epithelium. "Deletion of PTCH1 was also associated with the progression from early to advanced stages of cervical carcinoma and predicted poorer overall survival (OS) in patients." (PMID 34572373, 2021). "Subsequently, we found cervical cancer exosomes carrying large quantities of Hh-GLI signaling components like PTCH1." (PMID 34167524, 2021). "Moreover, CAR treatment also reduced the mRNA expression of PTCH1 by 0.82 ± 0.05, 0.54 ± 0.12, and 0.27 ± 0.06 fold in C33A cervical cancer cells." (PMID 36712982, 2022). "Cervical cancer exosomes were found to carry several upstream components of Hh-GLI signaling, out of these PTCH1 showed the highest protein content." (PMID 34167524, 2021). "The mRNA expression of key proteins such as PTCH1, SMO, and GLI1 was downregulated significantly, indicating that CAR may prevent cervical cancer by modulating hedgehog signaling powerfully." (PMID 36712982, 2022). "Earlier, we showed over-loading of Hh-GLI signaling components like PTCH1, Shh, and Ihh on cervical cancer exosomes regardless of the cell type." (PMID 34167524, 2021).
chondrosarcoma (4 papers, 2018 to 2024). A malignant cartilaginous matrix-producing mesenchymal neoplasm arising from the bone and soft tissue. "Deletions in tuberous sclerosis 1 (TSC1) and phosphatase and tensin homolog (PTEN) genes and nonsense and missense mutations in the protein patched homolog 1 (PTCH1) have been observed in central chondrosarcomas." (PMID 35163019, 2022). "Then, Using qRT-PCR, we measured the expression of IHH, PTCH1, SMO, and GLI1 and found that their levels were significantly lower in normal articular cartilage compared to any other chondrosarcomas, particularly in dedifferentiated chondrosarcoma." (PMID 37488121, 2023). "Expression of PTCH1, SMO, and GLI1 proteins was detected in chondrosarcoma patient tissues and three chondrosarcoma cell lines (HC-a, SW1353, and JJ012), but not in normal articular cartilage tissues." (PMID 30081498, 2018).
fibroma (4 papers, 2020 to 2023). A non-metastasizing neoplasm arising from the fibrous tissue. "Instead, loss of PTCH1 locus has been shown in cardiac fibroma tissue." (PMID 32964316, 2020). "The occurrence of malignant stromal tumours, which have not been reported yet in PTCH1-related GS where only fibromas have been reported, has to be underlined." (PMID 35768194, 2022).